RAB3D (RAB3D, member RAS oncogene family)
Diseases named in the same sentence as RAB3D in open-access papers (continued):
Sharing a sentence is not in itself a finding about the gene and the disease.
tumor (17 papers, 2015 to 2025). "In summary, our study provides an important theoretical foundation for us to understand the role of Rab3D in tumor progression and metastasis, suggesting that Rab3D is a potential diagnostic biomarker and a novel therapeutic target for anti-tumor metastasis." (PMID 25823663, 2015). "But here, the association between Rab3D and exosomes release in tumor is uncovered for the first time." (PMID 25823663, 2015). "Interaction prediction assays with miRNA and luciferase reporter assays also demonstrated the action of LINC01133 as a sponge for the miRNA miR-30b-5p, negatively regulating it and, as a consequence, increasing the expression of the Rab3D protein, which is directly associated with tumor growth." (PMID 40863724, 2025). "This suggests RAB3D could potentially serve as a broad-spectrum diagnostic biomarker for tumor progression relevant to both patient diagnosis and treatment." (PMID 29905536, 2018). "The role of circECE1/miR-588/RAB3D axis in regulating tumor metastasis in vivo needs to be further analyzed using various experimental models." (PMID 37559140, 2023). "Demonstrated by functional studies, increased expression of Rab3D increases tumour invasion and distant lung metastases." (PMID 34401050, 2021). "It was reported that RAB3D is highly expressed in tumor tissues and cells, and promotes the migration and invasion of tumor cells." (PMID 32154171, 2020). "Despite several studies emphasized Rab3D can promote tumor progression by targeting with signaling pathways, the precise molecular mechanism for the functional role of Rab3D in cancer remains elusive." (PMID 29423086, 2018). "Subsequently, we established in vitro migration and in vivo orthotopic metastatic mouse models to study the role of Rab3D in tumor metastasis." (PMID 25823663, 2015). "Increased expressions of Rab3D led to tumor invasion in vitro and lung metastasis in vivo, whereas Rab3D knockdown suppressed the tumor cell motility." (PMID 25823663, 2015). "To further test the significance of Rab3D in tumor progression, we next investigated the function of Rab3D in tumor metastasis and progression in vivo." (PMID 25823663, 2015). "In this study, we believe Rab3D has its potential as a therapeutic target in cancer and can be a novel option to treat tumor metastasis." (PMID 25823663, 2015). "Here, we reported that the expression levels of Rab3D were dysregulated in cancer cells and highly correlated with tumor malignancies in the clinical samples." (PMID 25823663, 2015). "MCF-7 cells transfected with N135I-Rab3D and T36N-Rab3D did not change their morphologies, while Q81L-Rab3D-expressing cells showed elongated protrusions, indicating that Rab3D enhances tumor cell motility depending on its GTP binding activity." (PMID 25823663, 2015). "We thus detected the EMT marker in Rab3D knockdown or overexpression tumor cells, and accordingly our data showed that Rab3D regulates EMT induction of tumor cells via the activation of Akt/GSK-3β/Snail pathway." (PMID 25823663, 2015). "To explore the role of Rab3D in tumor progression, we firstly analyzed the level of Rab3D in cancer cells." (PMID 25823663, 2015). "Conversely, stable knockdown of Rab3D in xenograft tumor model is sufficient to reduce metastatic colonies in the lung." (PMID 25823663, 2015). "Taken together, our results support that Rab3D is necessary and sufficient to promote tumor metastasis." (PMID 25823663, 2015). "We have demonstrated the critical role of Rab3D in the regulation of tumor cell motility, invasion and metastasis." (PMID 25823663, 2015). "Additionally, RAB3D expression levels are higher in BC cells and positively correlate with tumor stage." (PMID 38533085, 2024). "Interestingly, RAB3A, RAB3B and RAB3D were shown to promote breast, colon, esophagus, melanoma, osteosarcoma and glioma tumor progression by increasing cell proliferation, migration, and invasion." (PMID 38533085, 2024).
tumor (continued). "Finally, the cells stained for Ki-67 and RAB3D in tumor tissues of the sh-circECE1 group were fewer than those in sh-NC group, as measured by IHC assay." (PMID 37559140, 2023). "The secretion of tumor-derived exosomes (TEXs) is mainly attributed to the overexpression of Rab3D and the acidic tumor microenvironment, which carries information characteristic of malignant tumors, such as NKG2-D-ligand on the surface of melanoma-derived exosomes." (PMID 35890175, 2022). "Finally, results from a mouse xenograft model confirmed that knockdown of hsa_circ_0088732 induced miR-661 expression, resulting in suppression of RAB3D expression and inhibition of tumor growth in vivo." (PMID 32154171, 2020). "Furthermore, a positive correlation was found between Rab3D and tumor size expression levels (r = 0.346, P = 0.002)." (PMID 29423086, 2018). "Thus it is possible that Rab3D can promote tumor metastasis due to the secreted proteins from exosomes." (PMID 25823663, 2015). "But the inconsistence between mRNA and protein level changes implies that in the tumor cells there might be some important effectors to mediate the post-transcriptional regulation of Rab3D and its stabilization." (PMID 25823663, 2015). "To unravel the molecular mechanisms by which Rab3D regulates cancer progression, we focused on the epithelial to mesenchymal transition (EMT) induction, because the process of EMT has been documented to be associated with tumor progression and metastasis." (PMID 25823663, 2015). "Furthermore, the suppressions of Rab3D expression, which resulted in the deregulation of exosomes release and Hsp90α secretion, have repressed tumor cell motility and invasiveness." (PMID 25823663, 2015). "Thus, this study provides a novel insight into the biomedical relevance of Rab3D in tumor malignancies, which indicates that Rab3D plays a critical role in promoting tumor metastasis and is a promising therapeutic target for the treatment of cancer." (PMID 25823663, 2015). "Therefore, in fish, RAB3D also may promote antitumorigenic functions by recruiting immune cells to the tumor microenvironment." (PMID 34067095, 2021). "Furthermore, RAB3D was found to regulate epithelial-to-mesenchymal transition (EMT) and promote BC tumor cell motility, invasion and metastasis through the activation of the AKT/GSK-3β/SNAIL signaling pathway." (PMID 38533085, 2024). "To evaluate the expression status of Rab3D in CRC tissues, we examined the expression level of Rab3D in 80 matched CRC tumor and non-tumor tissues by RT-qPCR and immunohistochemical staining." (PMID 29423086, 2018). "In this study, the levels of Rab3D in the normal tissues or benign tumors are low, whereas the high levels of Rab3D are closely correlated with tumor TNM staging not grade, showing that Rab3D is a potential selective target for cancer progression." (PMID 25823663, 2015). "More importantly, the abnormal expression of Rab3D in cancer cells is not tissue- and tumor type-specific." (PMID 25823663, 2015). "Moreover, cellular transport was also compromised in tumor cells through downregulation of 38 proteins related to vesicle-mediated transport, as well as important proteins involved in vesicle docking involved in exocytosis (such as VPS33B, RAB3D, VAMP3, and SCFD1)." (PMID 39202022, 2024). "Notably, IHC staining showed that Rab3D was markedly increased in stage III-IV (P=0.002), but not related to tumor grade (P=0.208), showing a significant correlation between Rab3D expressions and cancer TNM stages." (PMID 25823663, 2015).
cancer (11 papers, 2015 to 2025). A tumor composed of atypical neoplastic, often pleomorphic cells that invade other tissues. "The enhanced release of exosomes from cancer cells is primarily associated with the overexpression of Rab3D, a member of the RAS oncogene family (Rab3D), activation of transduction pathways such as the Wnt pathway, and the presence of an acidic microenvironment that facilitates cell fusion events." (PMID 38243280, 2024). "Although 8 malignant cases had a Rab3D score of 0, there were 92 cases that were positive and all of the normal tissues had the score of 0, which indicated the good sensitivity and specificity of Rab3D as a diagnostic biomarker to detect carcinoma." (PMID 25823663, 2015). "Rab3D is a secretory small GTPase and in vitro and in vivo experiments established its critical function in cancer metastatic processes." (PMID 27096627, 2016). "More importantly, a significant positive relationship between Rab3D and the malignancy of cancer patients is observed." (PMID 25823663, 2015). "At first, we established the cancer cell lines stably overexpressing recombinant human Rab3D and stably transfecting with GFP-Rab3D shRNA, respectively." (PMID 25823663, 2015). "In the future, we can develop small-molecule inhibitors of Rab3D via rational drug design for the treatment of cancer." (PMID 25823663, 2015). "Tissues were scored on the basis of staining intensities of Rab3D expressions and the percentages of cancer cells stained." (PMID 25823663, 2015). "The levels of intracellular Rab3D in many types of cancer cells were significantly higher than that in the immortalized human microvascular endothelial cells (HMEC)." (PMID 25823663, 2015). "We detected protein levels of Rab3D in nine cancer cell lines and twelve types of clinical cancer specimens." (PMID 25823663, 2015). "Large scale, randomized, clinical trials are needed in the future to reveal that Rab3D is the valuable prognostic indicator for cancer patients in the clinic." (PMID 25823663, 2015). "RAB3D, member RAS oncogene family (RAB3D) is one of the key members of the Rab GTPase family and has been extensively studied for its ability to regulate important biological processes in various cancers." (PMID 37559140, 2023). "Furthermore, secreted Hsp90 has been reported as a driver of EMT events, which is consistent with our finding that secreted Hsp90 is essential for Rab3D-induced cancer cell migration and invasion." (PMID 25823663, 2015). "To investigate whether Rab3D is required for the invasive phenotypes of cancer cells, we knocked down Rab3D in highly invasive MDA-MB-231 cells and highly expressed Rab3D in non-invasive MCF-7 cells, respectively." (PMID 25823663, 2015). "Furthermore, the expression levels of phosphorylated AKT, phosphorylated GSK3β, ZEB-1 and snail-1, all of which are very important for EMT process during cancer progression, were significantly up regulated in Rab3D-MCF-7 cells, but decreased in siRab3D-MDA-MB-231 cells." (PMID 25823663, 2015). "Extensive genes have been identified as the target of miR-761 in numerous cancers, including HDAC1, Rab3D, Runx3, Mitofusin-2, CXCR1, TRIM29, MSI1, ING4, TIMP2, and GSK3β." (PMID 32185226, 2020). "COMMD7, ITGA1, RAB3D, and TNFAIP2 have all been shown to be upregulated in various cancers including PDAC." (PMID 28922540, 2017). "Overexpression of small GTPase and Rab3D may upregulate lung metastasis by triggering EMT via intracellular AKT/GSK-3β signaling and boosting the expression of Hsp90, ultimately enhancing cancer metastasis by activation of MMP2." (PMID 38243280, 2024). "Although Rab3D is widely expressed in several secretory tissues and even in rat pancreatic acinar tumor cell line AR42J cells, the biological function and molecular mechanisms for Rab3D in cancer have not been elucidated so far." (PMID 25823663, 2015). "However, the role of Rab3D in cancer was never systematically studied." (PMID 25823663, 2015).
infection (3 papers, 2024). The state of being infected such as from the introduction of a foreign agent such as serum, vaccine, antigenic substance or organism. "Moreover, Rab3D, a specific marker of secretory vesicle maturation, was downregulated in the lacrimal glands with EV-A71 infection, as shown by qRT-PCR." (PMID 38628549, 2024).
RAB3D also shares sentences with these, for which no sentence is quoted: benign breast tumors (1 paper); benign tumors (1); colon cancer (1); depression (1); non-small cell lung carcinoma (1); pan (1); pancreatic ductal adenocarcinoma (1); rectal cancer (1); renal cell carcinoma (1); Salmonella Infections (1).